EPCAM (epithelial cell adhesion molecule)
Diseases named in the same sentence as EPCAM in open-access papers (continued):
Sharing a sentence is not in itself a finding about the gene and the disease.
tumor (continued). "Additionally, we showed that EpCAM-regulated tumour development and treatment sensitivity is associated with activation of the PI3K/Akt/mTOR pathway." (PMID 30419852, 2018). "Moreover, clinical evidence showed that high HBx expression in human HBV-related HCC was statistically associated with the expansion of EpCAM + or OV6 + tumor cells, and aggressive clinicopathological features." (PMID 30177788, 2018). "30% of CTCs and 14% of tumor cells maintained expression of EPCAM even upon loss of ECAD." (PMID 29568081, 2018). "We constructed a second-generation CAR against the tumor-associated antigen EpCAM." (PMID 30410941, 2018). "EpCAM in HCC samples was significantly associated with tumor size and tumor number." (PMID 28156061, 2017). "Furthermore, EpCAM+ CTCs ≥ 2 were strongly associated with a shorter time of recurrence, greater vascular invasion, poor tumor differentiation and higher levels of alpha fetoprotein (AFP), an important HCC marker." (PMID 27738343, 2017). "We analyzed the tumor-associated transcripts EpCAM, MUC-1 and CA-125." (PMID 28388557, 2017). "Similar to the finding that EPCAM-PL was preferentially observed in poorly differentiated tumor components such as the tumor budding area of primary CRC tissues, the EPCAM-loss foci were predominantly detected in poorly differentiated tumor clusters of metastatic CRC lesions." (PMID 26528695, 2016). "This inference can be reasonable because it was suggested that tumor budding, which is closely associated with EPCAM-PL, might be related to poor response to chemotherapy or chemoradiotherapy in CRC according to previous studies." (PMID 26528695, 2016). "Characteristically, EPCAM-loss foci were localized in poorly differentiated tumor glands or clusters (including tumor budding) (74%), poorly cohesive tumor cells (including signet ring cells) (42%), and tumor-infiltrating lymphocyte-rich invasive borders (32%)." (PMID 26528695, 2016). "In addition to cytomorphological analysis, gene expression of tumor associated genes (Cytokeratin-18, Cytokeratin-19, Cytokeratin-20, Cytokeratin-7, EPCAM, MUC1, HER2, EGFR) and of leukocyte markers (e.g. CD45, CD68) was tested in enriched CTC fractions." (PMID 25862542, 2016). "Actually, we have evidence that soluble EpCAM can exist in two different forms: first as variant cleaved on the membrane of EpCAM positive tumor cells (EpEX), second, as full-length protein (EpCAM) expressed on tumor-derived exosomes." (PMID 25947366, 2015). "EpCAM shows oncogenic potential via the capacity to up-regulate c-myc, e-fabp, and cyclins A and E. EpCAM is exclusively expressed in epithelium and epithelia-derived neoplasms and therefore can be used as a diagnostic marker for various cancers." (PMID 26487959, 2015). "The loss of EpCAM and/or CK in tumor cells has been reported previously." (PMID 24886394, 2014). "Interestingly, also EpCAM (Epithelial cell adhesion molecule), one of the first tumor-associated antigens identified, was shown to be a β-catenin dependent signal transducer, and β-catenin is involved in nuclear signaling by EpCAM itself." (PMID 23016862, 2013). "In certain tumor types, EpCAM overexpression is linked to advanced stage of disease and worse overall survival, suggesting that EpCAM may have utility as a potential prognostic marker." (PMID 24362576, 2013). "In some publications EpCAM is argued to act as an intercellular adhesion molecule, and loss of EpCAM expression therefore reduces cell-cell adhesion, thereby promoting dissemination of tumor cells." (PMID 22646670, 2012).
tumor (continued). "The loss of membranous EpCAM expression has been found to significantly correlate with presence of lymph node metastasis and infiltrating tumor margins in colorectal cancers and in breast cancer, in addition to being linked to advanced stage of disease and poor overall survival." (PMID 23049733, 2012). "In the TACE group, the presence of high EpCAM staining was associated with tumor recurrence." (PMID 23216644, 2012). "Indeed, heterogeneous expression of epithelial surface markers has been previously reported in different tumor entities at tissue level, as well as the loss of EpCAM expression in the case of epithelial-mesenchymal transformation." (PMID 21595914, 2011). "Moreover, the ability to expand CD44+/CD24−/EpCAM+ cells was associated with the ability to support MCF7 tumor growth in vivo (respectively)." (PMID 21957456, 2011). "The loss of EpCAM or CK in tumor cells has been extensively described." (PMID 21577258, 2011). "Whether the recently reported regulated intramembrane proteolysis (RIP) mediated loss of EpCAM from the tumor cell surface might be one of the reasons for the limited efficacy of EpCAM-based cancer therapies remains to be established." (PMID 21152431, 2010). "In our previous study directly focusing on the expression of putative stem cell markers in EMT-derived tumour cells, we describe a low frequency of CD44s, CD166, and EpCAM staining within tumour buds, thus emphasising the loss of cell adhesion molecules typical of these cells." (PMID 20606680, 2010). "We hypothesise that our findings concerning decreased (rather than increased) expression of membranous CD166, CD44s, and EpCAM and their association with features of tumour progression are in large part a result of their cell adhesion function." (PMID 20606680, 2010). "The hypothesis that loss of EpCAM expression may be involved in cancer metastasis is further supported by the finding that EpCAM protein expression on circulating tumour cells (CTC) is reduced compared with primary and metastatic tumours." (PMID 21339979, 2010). "Generally speaking, high expression of EpCAM associated with a proliferative and regenerative phenotype in normal tissues with active sites of cell division, and with cancer-initiating cells in tumours in vivo." (PMID 19925656, 2009). "Likewise, EpCAM can now be considered to be one of the most frequently and most intensely expressed tumour-associated antigens known." (PMID 17211480, 2007). "Furthermore, a secreted targeted form of human CE2 (C28-sCE2) was constructed by fusing sCE2 to a human scFv directed against Epithelial Cell Adhesion Molecule (EpCAM), a tumour-associated antigen." (PMID 12237777, 2002). "Similar to the previous method, circulating tumor cells in peripheral blood from high-risk populations and cancer patients were enriched and identified using a positive sorting method that employed liposome magnetic beads targeting the epithelial cell adhesion molecule (EpCAM) and vimentin." (PMID 40076201, 2025). "To explore whether SpatialSNV is able to identify essential SNVs in tumorigenesis, we utilized transcriptomics data to divide the tumor section into the tumor (marked by EPCAM and other tumor-associated markers), tumor-adjacent margins (marked by VIM, COL1A2, PTPRC), and normal tissues." (PMID 40515555, 2025). "Therefore, high expression of the tumor marker, EpCAM, is often associated with poor prognosis." (PMID 36959784, 2023). "In addition, the quantity of polyploid (≥ pentasomy 8) EpCAM+ CTCs (cutoff: ≥ 1 cell), small EpCAM− CTCs with trisomy 8 (≥ 5 cells), positive detection of circulating tumor microemboli (≥ 1), and increased triploid CTCs were linked with a poor prognosis in postoperative patients." (PMID 36369033, 2022). "Moreover, EpCAM is associated with some miRNAs and genes involved in tumor progression." (PMID 35986321, 2022).
tumor (continued). "Therefore, EpCAM’s association with differential clinical outcome is complex and might vary depending on the origin of the tumor or even the stage of tumor progression." (PMID 32507912, 2020). "In accordance with these findings, we could show that combining CA.19-9 with serum exosomal miR-200b and miR-200c in total as well as EpCAM-positive serum exosomes improved the tumor marker’s diagnostic accuracy by 18%, yielding an AUC of 0.97, sensitivity of 92%, and specificity of 100%." (PMID 31941049, 2020). "Single nucleotide variants were analyzed and a total of 51 somatic variants were identified in tumor and EPCAM+CD44+CD49f+ samples compared to total lymph nodes, and of these we identified 20 synonymous variants, 26 non-synonymous variants, 3 insertion-deletions, and 2 unknown variants." (PMID 28487492, 2017). "Therefore we propose that a simultaneous increase of FGF19/FGFR4 associated with an increased level of EpCAM may help to identify which patients may have a more aggressive and resistant tumor biology requiring multi-drug therapy." (PMID 27447573, 2016). "EpCAM staining of agarose and paraffin embedded ascites tumor cells showed that cell aggregates in malignant ascites are mainly composed of tumor cells with only very few infiltrating or associated immune cells, thus comparable to EpCAM enriched single tumor cells." (PMID 25991672, 2015). "In this respect, reduced expression of EpCAM was also associated with epithelial-to-mesenchymal transition, and recently, a lack of EpCAM on CTCs has emerged and might offer a mechanism by which cells can escape the strict architecture of their tumor." (PMID 25477371, 2015). "CTC enrichment combined with a RT–PCR technology could already be used for the identification of tumor-related markers (EpCAM,MUC1, and ERBB2), EMT-associated transcripts (PI3Kα (phosphatidylinositol 3-kinase alpha), Akt-2, or Twist1), or stem cell markers such as ALDH1 (aldehyde dehydrogenase 1)." (PMID 25398926, 2015). "Therefore, despite the low expression of EpCAM on PC3 cells, targeting EpCAM may cause dramatic tumor-killing effects." (PMID 25636521, 2015). "Compared to primary and metastatic tissues the EpCAM expression has been reported to be approximately 10-fold lower on the cells shed into the circulation as part of the epithelial-mesenchymal transition, suggesting that loss of cell-cell adhesion is a prerequisite for tumor cell dissemination." (PMID 22530147, 2012). "Involvement of EpCAM in wnt signaling may ensure that a majority of TICs need to express EpCAM for proliferation and survival and that target loss may select a population of tumor cells with reduced tumorigenic potential." (PMID 20976159, 2010). "CTCs were enumerated using EpAb3-5 and a commercial EpCAM-based platform (MACS), and tumor EpCAM expression detected using EpAb3-5 was assessed by immunohistochemistry." (PMID 42038021, 2026). "Tumor EpCAM expression detected by EpAb3-5 correlated with nodal status (p < 0.01) but not T classification or overall stage." (PMID 42038021, 2026). "RHOJ promotes the function of tumor-associated endothelial cells and drives EMT through its interaction with the IPO9/EpCAM signaling pathway, thereby increasing cell survival and drug resistance." (PMID 41548474, 2026). "Stemness-associated genes such as GDF15, ALDH1L1, GPC3, AFP, EPCAM, CD44, and CD24 were predominantly expressed in tumor cells, with varying levels across other cell types including CAFs, TECs, and TAMs." (PMID 41493679, 2026). "Liquid biopsy analytes included CTCs and ctDNA assessed from peripheral blood plasma using EpCAM-based enrichment, targeted next-generation sequencing, whole-genome sequencing, or ultra-sensitive tumor-informed assays." (PMID 41827734, 2026). "Mechanistically, in vitro modulation of miR-26a-5p attenuated oncogenic signaling via the β-catenin/c-Myc/EpCAM axis, establishing its role as a tumor suppressor." (PMID 42089112, 2026).
tumor (continued). "By selectively targeting tumor-associated biomarkers such as MUC1, EpCAM, and nucleolin, these platforms enhance drug delivery efficiency, regulate oncogenic pathways, and minimize systemic toxicity." (PMID 41560835, 2026). "Functionalization with the EpCAM aptamer enables selective tumor recognition and enrichment, thereby improving therapeutic efficacy." (PMID 41560835, 2026). "Extending this approach, Zhao and colleagues developed EpCAM aptamer-functionalized cationic liposomes (MANPs) for targeted delivery of miR-139-5p, achieving efficient gene silencing and strong tumor inhibition." (PMID 41560835, 2026). "Conversely, the high-risk group exhibited significantly higher fractions of Ki-67+/PanCK+ and CD44+/EpCAM+ tiles, reflecting a proliferative tumor and cancer stem cell niche (P < 0.001 for all comparisons)." (PMID 41491099, 2026). "Blood isolated from PDX tumor-bearing mice was stained and detected in four channels: nuclear marker, PanCK/EpCAM, published cocktail, and total cocktail." (PMID 41543394, 2026). "Whole tumor analyses of EpCAM expression were conducted in patient samples with primary and recurrent HNSCC." (PMID 42178533, 2026). "The results showed that compared to LCC, the density of EPCAM+KLK6+ double-positive cells was significantly higher in RCC tumor tissues." (PMID 40932351, 2026). "IHC analysis in Cohort 4 showed that EPCAM expression was higher in tumor tissues than in peritumoral tissues." (PMID 41551611, 2025). "The chip uses superparamagneticnanoparticles coated with biotinylated antibodies to target exosomalmarkers such as tetraspanins (CD9, CD81) or tumor-specific markerslike EpCAM." (PMID 40720603, 2025). "In contrast, the tumor from Pt#9 tumor, characterized by high αSMA and low EpCAM expression, demonstrated poor treatment responsiveness." (PMID 41315187, 2025). "Colorectal cancer arises from the epithelial cells lining the colon or rectum, and these tumor cells are highly likely to express EpCAM on their surface." (PMID 40547026, 2025). "It was anticipated that the resultant EpCAM–CS‐co‐PNVCL@IR780/IMQ NPs would facilitate the targeted release of medication at the tumor site." (PMID 40391083, 2025). "EpCAM contributes to cell adhesion, proliferation, tumor initiation, and epithelial–mesenchymal transition (EMT)." (PMID 40806559, 2025). "CellSearch is tailored to detect known cell types, specifically circulating tumor cells that are EpCAM+, CK+, and CD45-, and relies on a predefined set of markers." (PMID 40617936, 2025). "For example, the epithelial cell adhesion molecule (EpCAM) is significantly upregulated in PCa tissues, correlating with tumour occurrence, progression and particularly bone metastasis." (PMID 39973042, 2025). "FACS can isolate tumor cells or cancer stem cells (CSC) by a specific biomarker such as EpCAM on the tumor cell surface." (PMID 40564859, 2025). "The co-expression of CD133 and EpCAM in LCSLCs marks a subpopulation with significant stem cell-like properties, contributing to tumor growth and recurrence." (PMID 40677705, 2025). "EpCAM showed strong specificity and low background fluorescence in all LN specimens, even at low tumor burdens." (PMID 41087662, 2025). "Circulating tumor cells can undergo epithelial‐mesenchymal transition (EMT) thereby reducing the expression of epithelial markers such as EpCAM and CK8/18/19 and increasing the expression of mesenchymal markers such as vimentin (Vim) and c‐MET." (PMID 38956984, 2025). "All PDGCAs expressed markers of tumor epithelial and stem cells (EPCAM, CDH1, KRT18, CA9, CD24, CD133), stromal and extracellular matrix components (COL3A1, COL5A1, DCN, PDGFRA, and PDGFRB), and mesenchymal stem cells (CD73, CD105, CD90)." (PMID 40723172, 2025). "The CTC-derived cell lines are able to independently form 3D structures that resemble the tumor of origin, retain positivity to EpCAM, and genetically exhibit 8q24.21 amplification containing the MYC oncogene." (PMID 40157906, 2025).
tumor (continued). "Catumaxomab is a trifunctional bsAb that binds to epithelial cell adhesion molecule (EpCAM) on tumor cells and CD3 on T-cells." (PMID 41211166, 2025). "In the NCI-H1781 and MCF7 models with high expression of both EpCAM and CLDN3, BsADC 3 demonstrated more potent anti-tumor activity than the EpCAM parental monoclonal ADC." (PMID 40057807, 2025). "IHC results revealed elevated EpCAM expression in both liver and lung tissues of the Vehicle group, indicating the extensive tumor infiltration." (PMID 40958869, 2025). "Low/null epithelial cell adhesion molecule (EpCAM) tissue expression makes cells prone to dissociating from each other and to disseminating from tumor bulk." (PMID 41008614, 2025). "This evaluation involved the utilization of blood samples spiked with tumor cells exhibiting varying EpCAM antigen profiles, thereby enabling a thorough assessment of the beads' efficacy in differentiating and capturing these distinct cellular entities." (PMID 39743435, 2025). "To further analyze the lipid metabolism pathway in GC cells, we identified tumor cells using the GC-specific markers EPCAM and CD24." (PMID 40694956, 2025). "EpCAM+ circulating tumor cells (CTCs) serve as biomarkers of disease progression and metastatic risk in OSCC." (PMID 39996844, 2025). "In contrast, TF and EpCAM were expressed at low, albeit detectable, levels in the majority of tumor regions." (PMID 40806559, 2025). "After 3 days of coincubation, we measured tumor killing by annexin staining of EPCAM+ tumor cells, and exhaustion was measured by LAG3, PD-1, TIM3, and CD39 expression on CD8+ T cells." (PMID 40459946, 2025). "Although TNBC E0771 tumors had a more highly activated immune environment, the tumors continued to demonstrate more aggressive tumor characteristics, including higher proportions of Ki67 + proliferating EpCam + tumor cells." (PMID 40585246, 2025). "CX-2051 is a masked EpCAM ADC carrying a next-generation camptothecin Topo-I payload designed for tumor-local activation." (PMID 41256852, 2025). "More research is required to assess this device using patient specimens, which contain tumor-specific antibodies like HER2 or EpCAM." (PMID 40305328, 2025). "In this study, [68Ga]Ga-Ec1-NOTA demonstrated the highest tumor-to-blood ratio, suggesting a potential advantage for visualizing EpCAM-expressing tumors." (PMID 40445498, 2025). "In conclusion, our study shows that NAG-1/GDF15, via its full-length pro-NAG-1/GDF15 form, functions intracellularly as a tumor suppressor by inhibiting the oncogenic protein EpCAM, which in turn reduces β-catenin and NF-κB signaling." (PMID 40316530, 2025). "While EpCAM FACS‐based analysis allowed rapid tumor cell detection, it also demonstrated that tumor cells usually represent only a minority of MPE cells." (PMID 40525275, 2025). "Circulating tumor cells are easier to detect than cells within the tumor mass because they can be identified from simple blood samples for markers like EpCAM." (PMID 40869256, 2025). "The anti-EpCAM sdAbs specifically bound to EpCAM complete extracellular domain and human cancer cells, leading to inhibition of cell proliferation, migration, invasion, and tumor growth in vivo." (PMID 40017594, 2025). "For instance, EpCAM is involved in cell-to-cell adhesion, cell proliferation, and cancer stemness, playing a role in tumor progression and treatment resistance." (PMID 40699639, 2025). "EpCAM is abundantly expressed in colorectal and hepatocellular CSCs, where it facilitates tumour proliferation, invasion, and metastatic spread." (PMID 41321388, 2025). "During the EMT process, tumor cells lose epithelial markers like EpCAM and acquire mesenchymal markers such as vimentin driven by transcription factors like Snail and Twist." (PMID 40260304, 2025). "Since EpCAM was the most abundant and consistent expressed TAA on PDAC patient tumor cells, the EpCAM-IgA antibody was tested in PMN ADCC assays with tumor cells and compared to PDAC cell lines." (PMID 40358156, 2025).